LIN28B (lin-28 RNA binding posttranscriptional regulator B)
Diseases named in the same sentence as LIN28B in open-access papers (continued):
Sharing a sentence is not in itself a finding about the gene and the disease.
prostate carcinoma (8 papers, 2014 to 2024). A carcinoma that arises from epithelial cells of the prostate gland. "This work clearly depicted LIN28B as a key initiator of a redifferentiation cascade, explaining the more aggressive growth pattern of prostate cancer cells." (PMID 37304235, 2023). "On the other hand, ESE3/EHF was repressed in cancer cells, which led to a rise of LIN28B protein levels and was crucial for cell transformation and expansion of prostate cancer stem cells." (PMID 37304235, 2023). "LIN28B was shown to be capable of activating other stem cell-related gene and stem-like gene networks in prostate cancer." (PMID 34548635, 2022). "Down-regulation of LIN28B reduced self-renewal ability and increased let-7 level in these prostate cancer cells." (PMID 28400788, 2017). "Expression of stem cell factors such as NANOG, SOX2, OCT4, and LIN28B was found to be upregulated in prostate cancer cells with an EMT phenotype." (PMID 28400788, 2017). "A microRNA profile (GeneChip hybridization) at 48 h upon transfection of DU145 prostate cancer cells using siRNA against Lin28B was determined." (PMID 25201220, 2014). "MicroRNA profiling in the androgen-independent prostate cancer cell line DU145 performed after silencing Lin28B by siRNA revealed up- and downregulations of several microRNAs with these most alterated being miR-212 and miR-2278." (PMID 25201220, 2014). "Lin28B is expressed in grade 2–3 prostate adenocarcinoma, and undifferentiated grade 4 prostate carcinomas." (PMID 25201220, 2014). "Lin28B has been presented to be tumorigenic in a prostate cancer mouse model but the role of Lin28B in androgen-independent prostate cancer is unidentified." (PMID 25201220, 2014). "We are proposing for the first time a novel oncogenic pathway in prostate carcinogenesis, involving Lin28B expression, miR-212 downregulation and activation of c-Myc oncogenic programs leading to the development of androgen-independent prostate cancer." (PMID 25201220, 2014). "Lin28b is a family of RNA binding proteins and microRNA regulators, which is involved in a potential regulatory feedback loop with miR122 via the activation of c-Myc in prostate cancer." (PMID 26244871, 2015). "Lin28B has been shown to be tumorigenic in a prostate cancer mouse model but the role of Lin28B in androgen-independent prostate cancer is unknown." (PMID 25201220, 2014). "Also, the expression of Lin28B protein positively correlated with the expression of the c-Myc protein in prostate cancer cells." (PMID 25201220, 2014). "Correlating well with previous data, miRNAs found to be upregulated upon Lin28B silencing in our present study include miR-212, downregulated in prostate cancer, and miR-146 which has been reported to suppresses tumor growth and progression in castration-resistant prostate cancer." (PMID 25201220, 2014). "Moreover, let-7 has been found to maintain the cancer stem-like cell (CSC) phenotypes of prostate cancer, let-7 expression is controlled by LIN28A and LIN28B, and loss of let-7 increases the expression of SOX2 and promotes the cell transformation and expansion of prostate CSCs." (PMID 37596700, 2023). "Therefore, our results may suggest that Lin28B is an oncogene suppressing miR-212 expression in androgen-independent prostate cancer cells." (PMID 25201220, 2014). "Combining existing reports with the analysis presented in this study, it can be inferred that RORC, AR, LIN28B, IRF9, and IRF3 promoted prostate cancer lineage plasticity through the RTK/RAS pathway." (PMID 38778150, 2024). "We found that Lin28B co-localized in the nucleus and cytoplasm of the DU145 androgen-independent prostate cancer cells." (PMID 25201220, 2014). "Lin28B co-localizes in the nucleus and in the cytoplasm of the DU145 prostate cancer cell line, indicating possible purpose in both cellular compartments." (PMID 25201220, 2014). "RORC, AR, LIN28B, IRF9, and IRF3 exert promotive roles in prostate cancer." (PMID 38778150, 2024).
prostate carcinoma (continued). "It is possible that Lin28B knock/down activates other molecular pathways not yet described, inducing alteration of these microRNAs in prostate cancer cells, relating them to Lin28B." (PMID 25201220, 2014). "There are few publications addressing the role of Lin28B in prostate cancer, and there are no publications addressing the function of Lin28B-microRNAs (different than let7)-c-Myc pathway in prostate cancer." (PMID 25201220, 2014). "Lin28B expression has recently been detected in the nuclei and cytosol of prostate cancer cells; with no substantial changes in its expression with increasing tumor aggressiveness as measured by Gleason score." (PMID 25201220, 2014). "Lin28B is expressed in all grades of prostatic carcinomas and prostate cancer cell lines, but not in normal prostate tissue." (PMID 25201220, 2014). "Lin28B protein was found overexpressed in prostate adenocarcinoma tissue, regardless the grade or Gleason score, and in prostate cancer cell lines but not in normal prostate cancer tissues." (PMID 25201220, 2014).
Wilms tumor (8 papers, 2016 to 2025). An embryonal neoplasm characterized by the presence of epithelial, mesenchymal, and blastema components. "These authors further showed that LIN28B expression in human Wilms tumor correlates with higher relapse risk and poor prognosis and that induced LIN28B expression in the embryonic mouse kidney caused this disease." (PMID 28400788, 2017). "Prolonged nephrogenesis was observed also in mice with overexpression of Lin28, Lin28b or inactivated Let-7 (Let-7a1; Let-7d; Let-7f1), which also either show direct tumorigenesis or activation of the Igf2 or H19h loci associated with pediatric kidney cancer Wilms' tumor." (PMID 34032268, 2021). "We have previously shown that continuous induction of LIN28B during embryonic development sustains and expands MM and/or nephron progenitors and blocks the final wave of nephrogenesis, ultimately resulting in oncogenic transformation resembling Wilms tumor." (PMID 30635573, 2019). "In rare cases, LIN28B expression may be activated in part through genomic amplification or in Wilms tumor by a chromosomal translocation." (PMID 28400788, 2017).
glioblastoma (7 papers, 2015 to 2025). The most malignant astrocytic tumor (WHO grade IV). "As a result, the authors argue that STAT3-mediated expression of LINC00520, which promotes the LIN28B expression, contribute to increased chemoresistance in glioblastoma through inhibited autophagy and reduced DNA damage." (PMID 37304235, 2023). "We have previously identified high-level expression of LIN28A and LIN28B in approximately 30 percent of pediatric and adult glioblastoma." (PMID 25638158, 2015). "However, LIN28B is involved in tumorigenesis in glioblastoma originating from neural stem cells (NSC), NSC-derived astrocytes, and oligodendrocyte precursor cells." (PMID 37304235, 2023). "In addition, our results showed that the Let-7 target genes (HMGA2, IGF2BP2, and LIN28B) were significantly upregulated in glioblastoma patient-derived cells (GBM04T) after anti-Let-7 treatment." (PMID 27102443, 2016). "Thus, it is likely that LIN28B also acts in glioblastoma as a regulator of Aurora A kinase and Ran." (PMID 37304235, 2023).
glioma (7 papers, 2013 to 2025). A benign or malignant brain and spinal cord tumor that arises from glial cells (astrocytes, oligodendrocytes, ependymal cells). "Clinically, high LIN28B expression correlates with poor prognosis in patients with GBMs, and lower-grade gliomas." (PMID 32651364, 2020). "The expression of Lin28B in glioma stem cells (GSCs; CSC2 cells) gradually decreased upon the induction of differentiation." (PMID 33311703, 2020). "To further quantify LIN28A and LIN28B expression in high-grade gliomas, we expanded our evaluation of GBM to include The Cancer Genome Atlas (TCGA) dataset containing more than 500 GBM samples." (PMID 23846349, 2013). "Therefore, according to the literature above, we wondered whether Sox2, Oct4, KLF4, Nanog, Lin28A and Lin28B contribute to glioma cell dedifferentiation in hypoxic environments." (PMID 34976166, 2022). "AVIL overexpression promotes glioma cell proliferation and migration by regulating FOXM1 and LIN28B." (PMID 39964147, 2025).
lung carcinoma (7 papers, 2017 to 2024). "In lung cancer, LIN28B has been linked to radio-resistance, as well as increased proliferation and migration in association with miRNAs." (PMID 37304235, 2023). "In clinical lung cancer samples, miR‐563 is negatively associated with LIN28B." (PMID 31766078, 2020). "For instance, in lung cancers, an AluJb element positioned upstream of the LIN28B oncogene operates as an alternative TSS, fostering cancer-specific expression of LIN28B isoforms." (PMID 37956335, 2024). "We found that by silencing LIN28B we were able to destroy the anti‐miR‐563‐accelerated cell proliferation in lung cancer." (PMID 31766078, 2020). "MiR‐563 can directly bind to the 3′UTR of LIN28B mRNA and repress its expression in lung cancer cells." (PMID 31766078, 2020). "To further confirm the function of LIN28B in miR‐563‐regulated cell proliferation in lung cancer, we disturbed the LIN28B expression in anti‐miR‐563‐contained lung cancer cells." (PMID 31766078, 2020). "To better illustrate the role of miR‐563 in lung cancer progression, we transfected miR‐563, anti‐miR‐563 and/or small interference RNAs targeting LIN28B mRNA into lung cancer cells and then analyzed the cell proliferation." (PMID 31766078, 2020). "We found that ectopic miR‐563 expression at the elevated concentration (50 and 100 nM) in lung cancer A549 cells was able to obviously induce the decrease in the luciferase activities of wt (wild‐type) vectors of 3′UTR of LIN28B." (PMID 31766078, 2020). "Collectively, we conclude that miR‐563 restrains lung cancer cell proliferation via inhibition of LIN28B." (PMID 31766078, 2020). "All our findings implied that miR‐563 was capable of directly targeting oncogenic LIN28B in lung cancer." (PMID 31766078, 2020). "All these findings indicated that the expression of LIN28B was restrained by miR‐563 in lung cancer cells." (PMID 31766078, 2020). "Together, our results indicate that miR-203 directly recognizes and binds to the 3′-UTR of the LIN28B mRNA transcript and suppresses LIN28B expression, which in turn enhances let-7 biogenesis in lung cancer cells." (PMID 28218277, 2017). "In this study, we found that miR-96 can inhibit the proliferation and promote the apoptosis of lung cancer cells and that LIN28B silencing can mimic the miR-203-induced cellular phenotypes." (PMID 28218277, 2017). "We also assessed the role of LIN28B in cell proliferation and apoptosis after the overexpression or silencing of LIN28B in lung cancer cells." (PMID 28218277, 2017). "Taken together, the findings of this study show that miR-203 directly targets LIN28B and enhances let-7 biogenesis to suppress tumor growth in lung cancer." (PMID 28218277, 2017). "Here, we report that miR-203 enhances the biogenesis of tumor suppressor let-7 in lung cancer by directly targeting LIN28B." (PMID 28218277, 2017). "Interestingly, EGCG has also been reported to upregulate let-7 miRNAs in human lung cancer and melanoma cells, consistent with possible LIN28B inhibition also in these cancer models." (PMID 38732012, 2024). "Indeed, the overexpression of fhit gene in H1299 lung cancer cell enhanced Lin28b expression at both mRNA and protein levels." (PMID 33437205, 2021). "In clinical lung cancer tissues, miR‐563 was downregulated and its target, LIN28B was upregulated." (PMID 31766078, 2020). "In summary, here we provide a novel role of miR‐563 in lung cancer growth via targeting LIN28B." (PMID 31766078, 2020). "Furthermore, our results confirmed that miR‐563 was able to repress the level of RNA and protein of LIN28B in lung cancer cells." (PMID 31766078, 2020). "MiR‐563 can target the LIN28B mRNA 3′UTR to restrain the expression of LIN28B in lung cancer cells." (PMID 31766078, 2020). "MiR‐563 plays a tumor suppressive role in lung cancer progression via targeting oncogenic LIN28B." (PMID 31766078, 2020). "The miR‐563/LIN28B signaling regulates the cell growth in lung cancer." (PMID 31766078, 2020).
lung carcinoma (continued). "Accordingly, we were interested in whether miR‐563 could target oncogenic LIN28B to affect the development of lung cancer." (PMID 31766078, 2020). "We then found that LIN28B was upregulated in 27 cases of human lung cancer tissues." (PMID 31766078, 2020). "The axis of miR‐563/LIN28B plays a key role in lung cancer cell growth." (PMID 31766078, 2020). "In this study, we discovered that miR-203 directly targets LIN28B in lung cancer cells, thereby disrupting the Lin28/let-7 circuit, enhancing let-7 biogenesis and consequently inhibiting the proliferation and promoting the apoptosis of lung cancer cells." (PMID 28218277, 2017). "Thus, miR-203 and its target, LIN28B, had opposite expression patterns and biological functions in lung cancer cells." (PMID 28218277, 2017). "Immunoblotting analysis confirmed that two different siRNAs targeting LIN28B mRNA (si‐LIN28B‐1 and si‐LIN28B‐2) could both effectively induce knockdown of LIN28B in lung cancer cells, and the interference effect of si‐LIN28B‐2 was more obvious than that of si‐LIN28B‐1." (PMID 31766078, 2020). "The new role of PCAF in mediating Lin28B acetylation and the specific release of its target microRNAs in H1299 cells may shed light on the potential application of let-7 in the clinical treatment of lung cancer patients." (PMID 29301498, 2018). "Finally, LIN28B was also shown to be involved in therapy resistance, particularly TKI-resistance in lung cancer." (PMID 37304235, 2023). "In lung cancer tissues, miR‐563 was decreased and negative correlation of miR‐563 and LIN28B was shown." (PMID 31766078, 2020). "A negative correlation exists between miR‐563 and LIN28B in clinical lung cancer samples." (PMID 31766078, 2020).
lymph node metastasis (7 papers, 2012 to 2024). "The present study demonstrated that high expression of Lin28 and Lin28B is associated with lymph node metastasis and poor prognosis of patients with oesophageal cancers." (PMID 22433967, 2012). "Importantly, overexpression of LIN28B significantly associated with advanced stages, lymph node metastasis and unfavorable prognosis in diverse cancers including oral cancer." (PMID 26478718, 2015). "In summary, we examined in the present study the clinical significance of Lin28 and Lin28B expression in oesophageal cancer and demonstrated that high expressions of Lin28 and Lin28B are associated with lymph node metastasis and poor prognosis of patients with oesophageal cancers." (PMID 22433967, 2012). "The expression of LIN28B increased with clinical stage progression and was significantly elevated in patients with lymph node metastasis." (PMID 38565547, 2024). "High expression of LIN28A and LIN28B correlated significantly with lymph node metastasis and poor prognosis." (PMID 32828126, 2020). "Second, the invasion assay was conducted to assess the role of Lin28B in lymph node metastasis by invasion to lymphatics." (PMID 22433967, 2012). "High expression of Lin28 and Lin28B correlated significantly with lymph node metastasis and poor prognosis." (PMID 22433967, 2012). "Similar to Lin28, high expression of Lin28B correlated significantly with lymph node metastasis (P=0.017) and lymphatic vessel invasion (P=0.002)." (PMID 22433967, 2012). "Notably, LIN28B expression increased significantly as the clinical stage progressed from I + II to III + IV and significantly increased in patients with lymph node metastasis." (PMID 38565547, 2024). "We also assessed whether Lin28B expression serves as an independent predictor of patients’ overall survival and found that tumor TNM stage, lymph node metastasis, recurrence, and distal metastasis, besides Lin28B expression, were associated with survival." (PMID 35173168, 2022).
melanoma (7 papers, 2017 to 2024). A malignant, usually aggressive tumor composed of atypical, neoplastic melanocytes. "Ultimately, they found that the TCF21/miR-10a-5p/LIN28B axis was at least partially responsible for melanoma progression." (PMID 37304235, 2023). "Recently, in 2021 a study demonstrated that the re-expressed miR-26a directly targeted and suppressed the LIN28B protein and the uridyltransferase Zcchc11 in prostate, melanoma and liver cancer in vitro and in vivo." (PMID 37304235, 2023). "Collectively, these results implied that TCF21/miR-10a-5p/LIN28B axis played a crucial role in the growth and invasion of melanoma." (PMID 34424910, 2021). "Here, we observed that miR-10a-5p attenuated the growth, invasion of melanoma by directly targeting and suppressing LIN28B expression." (PMID 34424910, 2021). "This study aims to confirm LIN28B as the targeted gene of miR-10a-5p which was explored in melanoma cells." (PMID 34424910, 2021). "We found that LIN28B expression was strongly decreased by TCF21 upregulation in the two melanoma cells." (PMID 34424910, 2021). "To conclude, miR-10a-5p was revealed to be highly expressed in melanoma tissues as well as cell lines, suppressing proliferation and progression of melanoma cells by directly regulating and blocking the expression of LIN28B." (PMID 34424910, 2021). "The result displayed that LIN28B expression were significantly diminished by TCF21 upregulation in the two melanoma cells." (PMID 34424910, 2021). "The reduction of the tumor-suppressive miR-26a induces an upregulation of LIN28B, which is a direct target of this miRNA, in diverse cancers including melanoma and HCC." (PMID 31906510, 2020). "In melanoma patients, LIN28B is often aberrantly expressed, reveals several oncogenic properties and is functionally required for melanoma progression." (PMID 31906510, 2020). "Overexpression of Lin28B reduced mature let-7 miRNA expression resulting in an enhanced sphere-forming ability of melanoma cells (sphere formation is a characteristic stem cell-like in vitro feature of many highly malignant cancer cells)." (PMID 31906510, 2020). "Further, clinical data indicated that Lin28B was aberrantly expressed in large number of melanoma patients." (PMID 28137308, 2017). "miRNA profiling revealed that miR-125a-5p suppresses melanoma growth through down regulation of TGFβ signaling by direct targeting Lin28B, a well known inhibitor of Let-7 miRNA biogenesis." (PMID 28137308, 2017). "Moreover, it has been found that LIN28B is essential for melanoma progression, since it drives a TGF-β signaling cascade in a 7-dependent manner." (PMID 37304235, 2023). "The TCF21/miR-10a-5p/LIN28B pathway could be targeted by a repressor in a new melanoma treatment in order to stop melanoma progression." (PMID 36982460, 2023). "Thus, when miR-98 was decreased, IL-6 and LIN28B were elevated and contributed to melanoma progression." (PMID 37304235, 2023). "In addition, we verified that the TCF21/miR-10a-5p/LIN28B axis played a key role in proliferation, invasion, migration in melanoma." (PMID 34424910, 2021). "Importantly, as for the four intersected target genes, LIN28B was most significantly raised in melanoma cells in comparison to that in normal controls." (PMID 34424910, 2021). "Furthermore, the data in our study suggested that LIN28B served as a direct target of miR-10a-5p in melanoma cells." (PMID 34424910, 2021). "In addition, the result also displayed that elevated miR-10a-5p expression blocked the proliferation, invasion and migration of in the both melanoma cells and this effect could be reserved by high LIN28B expression." (PMID 34424910, 2021). "TCF21 induced miRNA-10a targeting LIN28B could affect the progression and growth of melanoma." (PMID 34424910, 2021).